PROX1 (prospero homeobox 1)
Diseases named in the same sentence as PROX1 in open-access papers (continued):
Sharing a sentence is not in itself a finding about the gene and the disease.
soft-tissue tumors (1 paper, 2022). "There are no studies examining PROX1 as a prognostic marker in soft-tissue tumors." (PMID 35885529, 2022).
thyroid (1 paper, 2019). "In the current study, we asked whether similar behaviour and phenotypic changes following PROX1 depletion could also be observed in other FTC-derived cell lines, which would suggest that PROX1 regulation is important in follicular thyroid carcinogenesis." (PMID 31060342, 2019).
thyroid tumor (1 paper, 2019). A benign or malignant neoplasm affecting the thyroid gland. "Interestingly, PROX1 and FGF2 showed opposing expression levels in FTC tissues and seven thyroid tumor-derived cell lines." (PMID 31717665, 2019).
triple-negative breast carcinoma (1 paper, 2022). An invasive breast carcinoma which is negative for expression of estrogen receptor (ER), progesterone receptor (PR), and human epidermal growth factor receptor 2 (HER2). "The expression of PROX1 in patients with triple-negative breast cancer was higher than that in patients with non-triple-negative breast cancer." (PMID 35342346, 2022).
tumor (139 papers, 2006 to 2026). "They reported that a low degree of tumor differentiation (P < 0.0001) was linked to high expression of PROX1." (PMID 40660330, 2025). "In light of these findings, we aimed to investigate the association between PROX1 expression and histologic differentiation, lymphatic spread, and tumor growth in NSCLC, as well as to assess its prognostic relevance." (PMID 40843762, 2025). "Supporting a role in suppressing tumor initiation, Prox1 loss accelerated tumor formation in our HCC model." (PMID 39948437, 2025). "Tumors with low PROX1 expression (0–24%) were associated with a larger maximum tumor diameter (p = 0.026)." (PMID 40843762, 2025). "Specifically, decreasing PROX1 expression is associated with a reduction in both tumor size and the number of stem cells." (PMID 38244581, 2024). "Given the clinical association of PROX1 expression with glucose metabolism and tumor progression, we aimed to determine the specific effects of PROX1 on cell proliferation and glucose metabolism in CRC." (PMID 36594098, 2023). "In CRC, PROX1 promotes tumor progression, and high PROX1 expression is associated with adverse characteristics and unfavorable patient outcomes." (PMID 36815375, 2023). "Fourth, PROX1 deficiency or Ser79 phosphorylation renders tumour cells metabolically invulnerable and therapeutically resistant to metformin." (PMID 36433955, 2022). "Collectively, these findings demonstrate that the downregulation of PROX1 expression by AMPK is an important event for tumour metabolic adaptations during nutrient deficiency." (PMID 36433955, 2022). "Ιn ESCC, PROX1 seems to act as a tumor-promoting gene, since high levels were linked to a poor prognosis." (PMID 35885529, 2022). "That is, BCAA metabolism was enriched in K tumours in contrast to KL tumours that exhibited high PROX1 levels, suggesting PROX1 deficiency promoted BCAA degradation." (PMID 36433955, 2022). "Prox1 is implicated in the growth and progression of cancer and has been linked in different cancer types to both tumor-suppressive and oncogenic properties." (PMID 34183992, 2021). "The effect of PROX1 on the tumour development is strongly associated with its cellular localization, the tissue type and cancer stage." (PMID 31060342, 2019). "PROX1 is known to be upregulated in colon adenomas and is associated with a poor grade of tumor differentiation and with worse outcome, especially in women." (PMID 27283988, 2016). "In the present study, cancer cells were treated with human bone marrow MSC-conditioned medium (hBM-MSC-CM) for a period of time to allow the tumor cells to express the lymphatic vessel-associated markers Prox-1 and VEGFR-3." (PMID 25663886, 2015). "By immunohistochemistical analysis, Prox1 was shown to be closely associated with tumor progression (T factor and clinical stage), nodal metastasis, and LVD, and FOXC2 expression was shown to be significantly correlated with MVD in OSCCs." (PMID 24647631, 2014). "The transcription factor PROX1 (prospero homeobox 1) has a critical role in the development of various organs, and has been implicated in both oncogenic and tumor-suppressive functions in human cancers." (PMID 24797520, 2014). "Taken together, these findings indicate that PROX1 expression is associated with tumor differentiation and invasion, which are correlated with tumor progression." (PMID 24797520, 2014). "Prox1 expression was also associated with local progression of the tumor (T classification) (P = 0.0023), clinical stage (P<0.0001), and lymphatic vessel density (LVD) (P<0.0001)." (PMID 24647631, 2014). "Prox1 expression was significantly associated with local progression of the tumor (P = 0.0023), clinical stage (P<0.0001), lymphovessel density (LVD) (P<0.0001), nodal metastasis (P<0.0001), and worse prognosis (P<0.0001)." (PMID 24647631, 2014).
tumor (continued). "Age (P = 0.002), tumor size (P = 0.013), T-stage (P<0.001), N-stage (P = 0.004), M-stage (P<0.001), nuclear grade (P = 0.003), and PROX1 expression (P = 0.001) were significantly associated with a higher risk of death." (PMID 24797520, 2014). "In the context of cancer, increased PROX1 expression in tumor-associated lymphatic vessels has been associated with enhanced lymphangiogenesis and lymphatic vessel density, which could provide routes for cancer cell dissemination and lymphatic metastasis." (PMID 39328205, 2024). "In addition, PROX1 is overexpressed and associated with several tumor proliferation-associated genes, and its high expression confers worse prognosis of CRC 11-13." (PMID 36594098, 2023). "Given the clinical association of PROX1 expression with tumor progression in our cohort, we aimed to determine whether PROX1 expression is also a prognostic factor in CRC." (PMID 36594098, 2023). "To study whether PROX1 is related to tumor glucose metabolism, we analyzed the association between PROX1 expression in human tumors and glycolysis, measured as the maximum standardized uptake value (SUVmax), and patient prognosis." (PMID 36594098, 2023). "PROX1 served as a diagnostic marker for tumor-associated lymphatic endothelial cells." (PMID 35885529, 2022). "PROX1 has been shown to participate in the complex molecular mechanisms affecting tumorigenesis and has been associated with a plethora of clinicopathological parameters, including tumor stage and patients’ overall survival." (PMID 35885529, 2022). "Moreover, patients with higher PROX1 expression had an elevated risk of death and reduced OS rates after adjustments were made for age, sex, and tumor size." (PMID 35885529, 2022). "Consequently, the downregulation of miR-489 is linked to the overexpression of PROX1 and tumor spread, while conversely, miR-489 overexpression suppresses PROX1 expression and mitigates tumor proliferation and invasion." (PMID 35885529, 2022). "This unique expression pattern in both AMPK-proficient and deficient contexts suggests that PROX1 might be an important factor for tumour metabolic plasticity." (PMID 36433955, 2022). "While PROX1 expression is associated with tumour development and metastasis, its exact function in the process of tumorigenesis remains unclear." (PMID 31060342, 2019). "In CRC, high PROX1 expression was associated with high tumor grade." (PMID 27411302, 2016). "However, a clearer understanding of the underlying mechanisms through which PROX1 acts in different stages of tumor development will require further investigation." (PMID 24797520, 2014). "In the multivariate analysis, PROX1 was identified as an independent factor for survival (P=0.024), together with the presence of mutated isocitrate dehydrogenase 1 R132H protein, and with combined losses of chromosomal arms 1p/19q in oligodendrocytic tumours." (PMID 21559010, 2011). "High PROX1 expression was associated with a poor grade of tumour differentiation (P<0.0001)." (PMID 21970873, 2011). "However, the underlying mechanism of Prox1 in tumor genesis, formation, and progression are poorly understood and need to be exploited." (PMID 23675176, 2010). "Moreover, analysis of the correlation of PROX1 levels with clinicopathological data for patients with CRC showed that high PROX1 expression was positively associated with tumor depth of invasion (P = 0.031), lymphatic metastasis (P = 0.001), TNM stage (P = 0.002) and Ki67 immunostaining (P = 0.049)." (PMID 36594098, 2023). "However, as the accumulating evidence indicates that PROX1 is also implicated in the tumorigenesis of various cancer types, the scientific community has attempted to elucidate its complicated function in neoplasia pathogenesis, as well as its utility in cancer diagnosis, prognosis, and therapy." (PMID 35885529, 2022).
tumor (continued). "Inducing Prox1 OE after 21 days of HDTVI-mediated tumor formation also decreased glandular structures and reduced cholangiocyte marker expression (KRT19 and SOX9)." (PMID 39948437, 2025). "We combined the same model with doxycycline-inducible Prox1 OE to test the effect after tumor nodules had formed over 14 days post-HDTVI." (PMID 39948437, 2025). "While PROX1 has been studied in other malignancies—with mixed prognostic implications depending on the tumor type—its role in NSCLC remains undefined." (PMID 40843762, 2025). "This contrasts studies where Prox1 OE in tumor cells induced migratory and metastatic potential upon transplantation." (PMID 39948437, 2025). "In recent years, PROX1 has garnered increasing attention as a key regulatory molecule in cancer biology, owing to its remarkably context-dependent roles across diverse tumor types." (PMID 40843762, 2025). "PROX1, a member of the homeobox transcription factor family with both oncogenic and tumor suppressive characteristics, exhibited increased gene expression after PTPRG silencing." (PMID 41323734, 2025). "Crucially, although PROX1’s dual oncogenic and tumor-suppressive functions have been deeply investigated in a variety of malignancies, its relevance in NSCLC remains underexplored." (PMID 40843762, 2025). "Positive PROX1 and high MTA1 expressions were significantly associated with large tumor sizes (T3 & T4), presence of nodal and distant metastasis, advanced TNM clinical stage (III + IV), and presence of tumor recurrence (P values were ≤ 0.05)." (PMID 40660330, 2025). "The activation of β-catenin in the nucleus enhances the expression of PROX1, thereby promoting tumor lymphangiogenesis." (PMID 39866224, 2025). "Prox1 is expressed in many malignancies, and its involvement in tumorigenesis and tumor dissemination has been posited." (PMID 40909948, 2025). "Constitutive overexpression of Prox1-IRES-GFP led to fewer tumor nodules at the endpoint (6.7 versus 39.5 nodules), and all resulting tumors were GFP-negative, indicating selection against Prox1 OE." (PMID 39948437, 2025). "Compared to tumor tissues with low PROX1/high E-cadherin, those with high PROX1/low E-cadherin had a higher level of miR-9." (PMID 40660330, 2025). "Overexpression of Prox1 in tumor cells has been shown to inhibit both proliferative and transformational activities." (PMID 40909948, 2025). "PROX1 knockdown in primary tumor organoids with canonical gene expression induces the expression of fetal and non-canonical genes, suggesting that PROX1 functions to repress non-intestinal gene expression and safeguards lineage identity." (PMID 41221269, 2025). "This condition reflected not only to the proportion of tumor cell positivity, but also PROX1 intensity." (PMID 40843762, 2025). "PROX1 has both tumor-suppressive and oncogenic features according to the type of cancer and its expression is changed in a variety of human cancers." (PMID 40660330, 2025). "An inverse relationship was identified between the maximum tumor diameter and PROX1 expression levels in the 0–24% range." (PMID 40843762, 2025). "Constitutive Prox1 OE reduced tumor nodules at the endpoint (59.8 versus 245.2 nodules) and increased survival from 54 to 88 days." (PMID 39948437, 2025). "Subsequently, the expression levels of LYVE-1 in murine tumor tissues by IHC were strongly correlated with the circPDLIM5 levels, but the expression of PROX1 was low in tumor tissues." (PMID 40611320, 2025). "According to data extracted from the GEPIA (Gene Expression Profiling Interactive Analysis) database, in cases of NSCLC, PROX1 expression is reduced in tumor tissues compared to normal paired lung tissues." (PMID 40843762, 2025). "In this study, we demonstrate that the inhibition of GSK3B expression reduces β-catenin phosphorylation and promotes PROX1 transcription, leading to tumor lymphangiogenesis." (PMID 39866224, 2025).
tumor (continued). "Expression of PROX1 or α-SMA was significantly correlated with tumor size and histological type (pPROX1 <0.001, p-SMA <0.001 for both); however, neither PROX1 nor α-SMA expression correlated with patients’ sex or age." (PMID 38244581, 2024). "The result indicated PROX1 was overexpressed in tumor tissue compared with its normal counterpart; furthermore, loss or gain of PROX1 attenuated cell proliferation, migration, and invasion, both in vivo and in vitro." (PMID 38244581, 2024). "It is regulated by Prox1 and is involved in tumor cell-induced platelet aggregation, tumor metastasis, and lymphatic vessel formation." (PMID 39682237, 2024). "More to the point, CAFs with PROX1-knockdown demonstrated significantly lower wound-healing ability—that is, less migration and tumor-sphere generation." (PMID 38244581, 2024). "Significantly lower tumor weight and volume were discovered in the PROX1-shRNA#1 group compared with the control groups." (PMID 38244581, 2024). "The study revealed that high levels of PROX1 and α-SMA in CRC tissues are linked to increased tumor cell invasiveness and higher tumour-node-metastasis (TNM) stages." (PMID 38244581, 2024). "In the cases of human IBC, similar membrane podoplanin, membrane LYVE1, and nuclear Prox1 immunoreactivities were observed surrounding the tumor emboli." (PMID 39669476, 2024). "PROX1 is highly expressed in various malignant tumors and is involved in tumor cell differentiation, proliferation, migration, apoptosis, invasion, and tumor lymph node metastasis." (PMID 39328205, 2024). "We assessed the interplay between CAF-associated α-SMA and PROX1, and the impact of these interactions on tumor aggression by coculturing PROX1-expressing CRC cells (SW-480, SW-620, HCT116, and HT-29 cells) with α-SMA-rich CAFs." (PMID 38244581, 2024). "Targeting prospero homeobox 1 abrogated neuroendocrine characteristics and led to a decrease in cell proliferation in vitro and tumor growth in vivo." (PMID 39470735, 2024). "Despite these anti-tumorigenic roles of Prox1, previous reports suggest that Prox1 promotes tumor initiation and progression in other cell types and tissues." (PMID 37508533, 2023). "Overexpression of LINC00968 inhibited BC cell proliferation, migration, and tube formation in vitro as well as tumor growth in vivo through inhibition of miR-423-5p, which downregulated PROX1." (PMID 37175800, 2023). "To confirm the clinical significance of PROX1 in CRC, we analyzed PROX1 protein expression in 217 paired tumor tissues and adjacent normal colorectal epithelial tissues (from the FUSCC cohort) by IHC." (PMID 36594098, 2023). "RAMP2+ tumor endothelial cells (TECs) and PROX1+ lymphatic endothelial cells (LECs), were reduced in the PD-1+SMI group and highly expressed VEGF-associated receptor gene KDR (VEGFR1) and FLT1 (VEGFR2) compared with other endothelial subclusters." (PMID 37430270, 2023). "In the present study, we found that PROX1 was markedly upregulated and positively correlated with tumor cell glycolysis in CRC." (PMID 36594098, 2023). "Univariate Cox proportional hazards analysis showed that the PROX1 and Ki67 IHC scores; tumor differentiation (histologic grade) and size; vascular invasion; lymphatic metastasis; and TNM stage were prognostic factors for OS and DFS in CRC patients." (PMID 36594098, 2023). "Here, in correlation with transcriptome data, we demonstrated the detectable protein expression of KDR, FLT4, UNC5A, ADAM12, CD34, and Prox-1 in the human KS tumor microenvironment." (PMID 37046832, 2023). "To mechanistically explain the involvement of Prox1 in the regulatory network of tumor inhibitory factors, we initially examined its ability to control the expression of key players in cell proliferation and metabolism." (PMID 37508533, 2023). "In agreement with a tumor suppressing function, over-expression of Prox1 in both MDA-MB-231 and MCF7 cells significantly inhibited cell migration and invasion." (PMID 37508533, 2023).